IL13 (interleukin 13)
Diseases named in the same sentence as IL13 in open-access papers (continued):
Sharing a sentence is not in itself a finding about the gene and the disease.
Allergy (continued). "For instance, IL4, IL13 IL10, and IFN-γ, which are anti-inflammatory/regulatory cytokines, can modulate inflammatory processes like allergies and intestinal inflammatory diseases by regulating the immune response of the T helper 2 cells (Th2) and the T helper 1 responses (Th1)." (PMID 39891859, 2025). "Currently available IL-4-, IL-5-, and IL-13-targeted therapies underscore the translational gap between the established indication in allergic diseases and the lack of clinical evidence in obesity." (PMID 41007770, 2025). "In turn, the histamine increases the secretion of Th2 cytokines such as IL-4, IL-5, and IL-13 and inhibits the production of the Th1 cytokines IL-2 and IFN-γ through the upregulation of prostaglandin E2 and nitric oxide, thereby exacerbating the allergy." (PMID 39403377, 2024). "The expert panel consistently considered the use of anti-IL-4/IL-13 or anti-IgE appropriate overall, regardless of the presence of allergy in UAD patients." (PMID 37088840, 2023). "Consensus was achieved on several statements related to the indication for biologics in patients with UAD, such as the use of anti-IL-4/IL-13 or anti-IgE regardless of the presence of allergy (M: 8), although the level of agreement was lower among allergists." (PMID 37088840, 2023). "No allergy-related inflammation of any kind has occurred (e.g., ‘interleukin-4 and interleukin-13 signaling’), as presented in S2 Fig, and S7 Table." (PMID 37053215, 2023). "Our results showed that HPE could inhibit the production of IL-4, IL-6, IL-13 and TNF-α released by mast cells, thus, ultimately, compromised mast cell-mediated allergic diseases." (PMID 38012745, 2023). "The results showed that hydrogen inhalation significantly alleviated the symptoms of sneezing and pruritus, reduced the infiltration of inflammatory cells into the mucosa, and decreased the levels of IL-5, IL-13, and MCP-1 in serum, indicating the value of hydrogen in treating allergic diseases." (PMID 37007020, 2023). "Finally, STAT6 inhibitors are being developed and are logical candidates for allergic disease because of the important role STAT6 plays in IL-4 and IL-13 signaling." (PMID 36230993, 2022). "An important issue that needs to be emphasized considering in vitro tests is the fact that cytokines are determined in various conditions and various diseases; however, only certain cytokines (i.e., TNF-α, IL-2, IL-4, IL-5, IL-6, IL-10, IL-13, and IFN-γ) are important in allergic reactions." (PMID 36590449, 2022). "In allergy, it was shown to suppress allergic airway responses by inhibiting group 2 innate lymphoid cell (ILC2) activation, and decreasing the production of the Th2 cytokine IL-13." (PMID 34943923, 2021). "Our findings are consistent with those reported by a clinical study where DHA + EPA (fish oil) supplementation in Th2 biased allergy prone infants showing increased Th1 cytokines (IFN-γ and TNF-α) and reduced Th2 cytokine (IL-13) to PHA (mitogen stimulating T cells)." (PMID 34790691, 2021). "Repetitive exposure to ODE did not induce an increase in the Th2 cytokines IL-4, IL-5, and IL-13 which are known to be involved in the classical allergy response and agrees with the lack of MyD88 involvement in regulating serum IgE levels." (PMID 32321514, 2020). "IL-13 plays a critical role in allergies and exogenous IL-13 can induce AHR in absence of T and B cells." (PMID 29854835, 2018). "In addition, mast cells are the sources of several cytokines like pro-inflammatory interleukins (IL1β, TNFα and IL6), interleukins related to tissue repair and allergy (IL4, IL5 and IL13), chemokines (CXCL8 and CCL2) and the growth factor VEGF." (PMID 29232822, 2017). "(ii) In the allergy propagation phase, re-exposure to ingested food antigens activates emigrated antigen-specific CD4+TH2 memory/effector cells in the small intestine to produce IL-13, resulting in the increase of intestinal IL-25 production." (PMID 27853507, 2016).
Allergy (continued). "The results showed that the levels of IL-4 and IL-13 were higher in UC patients with FA than those UC patients without allergy." (PMID 27167186, 2016). "We identified seven cytokines from previous glioma or allergy literature (IL4, IL13, IL5, IL6, IL10, IFNG and TGFB2) to determine whether, they were associated with glioma before diagnosis." (PMID 26352148, 2015). "Our data which confirms the importance of BRP-39 in HDM-induced inflammation imply that BRP-39, in the context of allergy, is part of an immune inflammatory pathway crucial to mononuclear cell and eosinophil recruitment that is not dependent on IL-1 or IL-13." (PMID 21473774, 2011). "Since acetate did not directly affect IL‐13 production capacity of lung T‐cells, it may indirectly play a role in allergy development." (PMID 40760338, 2025). "Dupilumab, a monoclonal antibody targeting the interleukin-4 receptor α (IL-4Rα), blocks the signalling of both IL-4 and IL-13, key mediators of the Th2 inflammatory axis involved not only in atopic dermatitis but also in the development of other allergic diseases such as asthma." (PMID 41002407, 2025). "While we observed modulation in certain major cytokines associated with the development and regulation of allergies, such as IFN-γ and IL-13, we did not detect any modulation in the production of IL-4 and IL-17, which are also significant cytokines in allergic responses." (PMID 38538762, 2024). "Interestingly, in an intestinal anaphylaxis mouse model (BALB/c), diarrhea developed in wild-type mice, but not in IL-13 knockout mice, indicating a role of IL-13 in allergy-induced diarrhea." (PMID 35805922, 2022). "TLR3 and IL‐13 may induce the phosphorylation of JAK1, resulting in allergic reactions." (PMID 33534941, 2021). "Increased levels of IL-13, according to the Th2 response after traffic-related PM2.5 exposure, might stimulate goblet cell differentiation and MUC5AC production at the conjunctivae, which is a common pathogenesis in allergic diseases." (PMID 32344779, 2020). "When considering the harmful effects arising from excess IL-4 and IL-13, in for example allergies, knowledge of the structural and functional characteristics of the IL-4 receptors and their unique signaling via STAT6 has been useful in efforts to therapeutically modify IL-4/IL-13 biology." (PMID 29930549, 2018). "However, IL-13 and CD14 genes are good candidate genes in terms of allergic susceptibility and innate immunity since several studies have shown that IL-13 rs1295685 and CD14 rs20541 play an important role in the development of allergic diseases in Korean children." (PMID 24848505, 2014). "Furthermore, IL-13 levels did not correlate with a history of allergic diseases." (PMID 36078882, 2022). "Therefore, sustained upregulation of TLR4 in allergy may lead to pronged release of pro‐allergy factors (e.g., IL‐13 or IL‐4), rather than typical proinflammatory cytokines." (PMID 33900054, 2021). "Our findings did not align with the classical regulatory pattern of allergy development, where a reduction in IFN-γ typically coincides with the induction of IL-4, IL-13, and IL-17." (PMID 38538762, 2024). "Important for the context of allergic diseases is the fact, that CD38+ CD4+ T cells were characterized to be hypo-proliferative with a specific bias towards IL-13 secretion (with no change toward IL-4 or IL-5 secretion)." (PMID 38318168, 2024). "In patients with allergies, some studies showed that, in BALF, IL-5 and IL-13, but not IL-4, levels increased when compared with those of healthy patients." (PMID 23283149, 2009).
eosinophilia (366 papers, 2006 to 2026). "Th2-associated cytokines, including interleukin (IL)-5 and IL-13, are frequently elevated in eosinophilic adenoidal or sinonasal inflammation, correlating with tissue eosinophilia, goblet cell metaplasia, and corticosteroid responsiveness." (PMID 40868875, 2025). "One study demonstrated that a hybrid subset of pathogenic ST2+ ILC2s that produced both IL-13 and IL-17A promoted increased lung eosinophilia after exposure to protease allergen." (PMID 40777291, 2025). "These chemokines are induced by Th2 cytokines (IL-4 and IL-13) and work synergistically with IL-5 to drive eosinophilia, a hallmark of helminth infections." (PMID 40872306, 2025). "The cytokines such as IL-4, IL-5, and IL-13 are released causing eosinophilia and the pro-inflammatory cytokines like IFN-γ, TNF, IL-6, and IL-15 are increased promoting systemic inflammation." (PMID 41229508, 2025). "IL-4 and IL-13 promote the completion of IgE antibody type switching by B lymphocytes; IL-5 increases eosinophilia; IL-13 is associated with abnormal proliferation of goblet cells, mucus hypersecretion and airway hyper reactivity (AHR)." (PMID 38579176, 2024). "Elevated levels of IL-4, IL-5, and IL-13 are noted in patients and are associated with increased peripheral eosinophilia and IgE levels, which are common features of this disease." (PMID 39139309, 2024). "They show the highest expression of IL-13/Th2 and type 2 innate lymphoid cells (ILC2s), which are associated with increased sputum eosinophilia." (PMID 38474348, 2024). "T-bet deficiency results in the loss of IFN-γ production, and in turn is linked to the excessive production of IL-5 and IL-13 by Th2 cells, leading to the development of upper airway allergic inflammation and eosinophilia." (PMID 37727514, 2023). "IL-5 represents the key driver of eosinophilia, while the Il-4/IL-13 inflammatory pathway is strongly associated with FeNO, which, in turn, correlates with eosinophilic inflammation in the airways." (PMID 37947596, 2023). "Fungi-induced production of eosinophilia-associated cytokines, such as IL-5 and IL-13, from nasal mucosa and epithelial cell-derived cytokines, the initiating mediators of type 2 immune responses." (PMID 36362100, 2022). "Th2 cells are classically regarded as important effector cells that produce the hallmark cytokines IL-4 and IL-13, but also IL-3 and IL-5 that promote basophilia and eosinophilia, respectively." (PMID 35844529, 2022). "Of these, IL‐5 and IL‐13 are hallmark cytokines of type 2 inflammation, involved in eosinophilia, smooth muscle cell contraction and mucus secretion, and TNF is important in several inflammatory diseases." (PMID 34873877, 2022). "As Th2-mediated responses that underlie airway eosinophilia and airway hyperresponsiveness have been linked to IL-4, IL-5, and IL-13, we measured the levels of these cytokines in the BAL of OVA-exposed mice." (PMID 34744763, 2021). "IL-5 and IL-13 cause eosinophilia and smooth muscle cell contraction respectively, altogether contributing to the pathogenesis of asthma." (PMID 30524437, 2018). "SP-A and SP-D-deficient mice are inherently hypersensitive to pulmonary infections, showing increased eosinophilia and IL-13, a Th2-associated cytokine." (PMID 29696023, 2018). "AD is characterized as a Th2 disease with the abundant production of Th2 cytokines, such as interleukin IL-4, IL-5 and IL-13 associated with eosinophilia and elevated serum IgE level." (PMID 28434120, 2017). "Mice infected with helminths inducing eosinophilia, elevations in IL-4, IL-13 and other cytokines associated with alternative activation of macrophages (M2) in white adipose tissue (e.g. IL-4, IL-13) show improved glucose tolerance and reduced fat mass." (PMID 27666719, 2016). "Helminth infections were strongly associated with eosinophilia and hyper-IgE as well as with a Th2-polarized response (increased levels of IL-13, IL-10, and IL4/IFN-γ ratios and decreased levels of IFN-γ)." (PMID 27882241, 2016).
eosinophilia (continued). "SP-D gene deficient mice were found to exhibit hyper-eosinophilia and increased levels of IL-5 and IL-13 upon Aspergillus fumigatus allergen challenge, a response that was reversible by treating the mice with SP-D." (PMID 25848896, 2015). "IL-4 and IL-13 are potent inducers of eotaxin chemokines that can explain the eosinophilia associated with Th2 responses." (PMID 24693457, 2014). "Increased number of mucous cells has been associated with increased IL-13, inflammation and eosinophilia." (PMID 24138138, 2013). "The IL-13 gene is located on chromosome 5q, which has been suggested to be associated with the risk of elevated serum IgE levels, eosinophilia, airway hyper-sensitiveness and the occurrence of childhood asthma." (PMID 23382814, 2013). "In many cases, eotaxin caused substantial airway eosinophilia and, in conjunction with IL-5, and IL-13, caused an even more marked increase in eosinophils." (PMID 22203879, 2012). "Expression of IL-4, IL-5 and IL-13 are associated with airway hypersensitivity, eosinophilia, abundant plasma cells and pathological changes in the lungs." (PMID 21765962, 2011). "Previous studies on atopic dermatitis suggest that skin lesions accompanied by topical eosinophilia and systemic IgE elevation are associated with Th2 cytokines (IL-4, IL-5, and IL-13)." (PMID 21197410, 2010). "ZnONP treatment was associated with significant increases in eotaxin and IL-13, consistent with the severe acute eosinophilia observed after ZnONP treatment." (PMID 20729176, 2010). "In AD, most side effects—such as conjunctivitis, eosinophilia, and arthritis—are linked to IL-4 and IL-13 blockade, which may lead to increased IL-17 activity." (PMID 41481132, 2026). "The characteristic Th2-related cytokines (Il4, Il5, Il13) were markedly increased in AD-like lesions, while Il4 and Ccl11 expression was elevated to various extent in PN-like lesions appeared to be associated with dermal eosinophilia." (PMID 41229431, 2025). "Furthermore, IL-13 has been linked to eosinophilia, where it functions in conjunction with IL-5 to facilitate eosinophil activation and migration." (PMID 39594470, 2024). "TH2-associated cytokines such as IL-4, IL-5, and IL-13, which are often detectable in the presence of eosinophilia, may play a role in EDHM’s pathogenesis." (PMID 39219952, 2024). "Finally, in an ovalbumin-induced murine model of allergic airway disease, NK-deficient mice had decreased airway inflammation and eosinophilia, decreased secretion of IL-4, IL-5, and IL-13, as well as diminished OVA-specific antibody production." (PMID 36250466, 2022). "Here we show that Hp‐TGM could alleviate airway and lung tissue eosinophilia, in association with control of IL‐5 and IL‐33 cytokine levels at 24 h, or either IL‐4 and eotaxin‐1, or IL‐4 and IL‐13 responses in T‐cell mediated models." (PMID 35758054, 2022). "Given that IL-33 induces type-2 cytokines from ILC2, the attenuated eosinophilia in ob/ob mice may have been associated with a decrease in IL-5, IL-13, and eotaxin." (PMID 34074279, 2021). "Chronic schistosomiasis has been instigated in granuloma formation, tissue eosinophilia, collagen deposition and fibrosis driven by IL-13 cytokine may cause significant morbidity and mortality." (PMID 34048465, 2021). "In addition to eosinophilia, type-2-associated mucosal immunity is linked to goblet cell expansion to aid in parasite expulsion and is regulated by IL-13 production from type-2 innate lymphoid cells in the gut26,27." (PMID 31221971, 2019). "In particular, administration of somatic extract of M. marshalli during OVA sensitization resulted in reduction of Th2 associated immune responses including IL-4 and IL-13 and IgG1, as well as inflammatory cells infiltration, eosinophilia and goblet cells hyperplasia." (PMID 28494800, 2017). "Indeed, hybrid Th1/2 cells from the lungs contained fewer IL-13 and IL-5 producers than Th2 cells, associated with milder eosinophilia and reduced mucus production." (PMID 23976880, 2013).
eosinophilia (continued). "Importantly, we also observed the level of IL-13 associated with the induction of eosinophilia in FI-RSV or vacvG-immunized mice challenged with live RSV was reduced." (PMID 21980478, 2011). "Interestingly, expression of GATA-3, CCR3, -4, -8, and ST2L, and the generation of blood eosinophilia, is intact in mice doubly deficient in both IL-4 and IL-13." (PMID 18315837, 2008). "Additionally, the IL-13 R130Q variant has been linked to eosinophilia, and the latter has been shown to predict cardiovascular and cerebrovascular mortality possibly through endothelial inflammation and ultimately atherosclerosis." (PMID 18949100, 2008). "IL-13 overexpression in an inducible transgenic murine model causes esophageal eosinophilia and stricture formation; turning off IL-13 overexpression to remove allergic inflammation reduces tissue eosinophilia but is unable to reverse the established esophageal stricture." (PMID 28831387, 2017). "Dupilumab (targeting IL-4/IL-13) and mepolizumab (targeting IL-5) have shown promising results in reducing mass size and eosinophilia in patients who respond poorly to conventional therapies." (PMID 41527674, 2026). "The type 2 immune cytokines IL-4 and IL-13 are essential for eosinophil recruitment to the allergic lung, as depletion of both cytokines abolishes eosinophilia." (PMID 40276331, 2025). "While markers for identifying the T2-high phenotype are well established, IL-4, IL-5, IL-13, IgE, eosinophilia, and high FeNO levels, evidence for T2-low biomarkers remains limited." (PMID 40003269, 2025). "Th2 cells are main producers of IL-4 and IL-13 and were thought to be the crucial driver of eosinophilia." (PMID 40276331, 2025). "Eosinophilic adenoiditis or otitis media, defined by IL-5 or IL-13 expression and tissue eosinophilia, are more likely to respond to corticosteroids or anti-IL-5 biologics." (PMID 40868875, 2025). "Mice with transgenic expression of IL-25 exhibit eosinophilia and elevated levels of IgE, IgG1, IL-5, and IL-13." (PMID 39962262, 2025). "In contrast to SLPI KO mice treated with the control solvent, BPTI-treated SLPI KO mice showed reduced airway inflammation, fewer total BAL cells, and lower ratios of eosinophilia and Th2 cytokines, including IL-5 and IL-13, in BAL fluid." (PMID 40546642, 2025). "Type 2 inflammation is driven by the cytokines IL-4, IL-13, and IL-5, leading to eosinophilia, elevated IgE levels, and activation of eosinophils and mast cells within tissues." (PMID 41210306, 2025). "Eosinophilia on dupilumab is likely related to downstream cytokine effects from IL-4 and IL-13 blockade." (PMID 40863432, 2025). "Although dupilumab is generally well tolerated, eosinophilia due to inhibition of IL-4-/IL-13–mediated chemokines and adhesion molecules that assist with eosinophil migration from blood into tissue has been observed." (PMID 40778341, 2025). "As a matter of fact, in Western Countries, CRSwNP is well known to be predominantly characterized by Type 2 inflammation with pronounced eosinophilia and the presence of high levels of Type 2 cytokines, such as IL-4, IL-5 and IL-13." (PMID 41295249, 2025). "In vivo, CD4-specific conditional IP KO mice (CD4Cre+IPflox) exhibited exacerbated lung inflammation following exposure to Alternaria alternata extract, marked by increased IL-5 and IL-13 production, enhanced eosinophilia, and elevated mucus production." (PMID 40587812, 2025). "Activated Th2 cells release cytokines, including IL-4, IL-13, and IL-5, inducing eosinophilia in tissues and peripheral blood." (PMID 39521708, 2025). "The innate response to STHs comprises the release of cytokines, such as IL-4, IL-5, and IL-13, which drive eosinophilia, mast cell activation, and IgE production, which are key mechanisms required for the expulsion of parasites." (PMID 40872306, 2025).